IL20 (interleukin 20)
Diseases named in the same sentence as IL20 in open-access papers (continued):
Sharing a sentence is not in itself a finding about the gene and the disease.
infection (18 papers, 2013 to 2025). The state of being infected such as from the introduction of a foreign agent such as serum, vaccine, antigenic substance or organism. "Altogether, these data revealed that IL-20 overexpression was associated with an increased lung permeability in response to PVM infection, a process associated with intercellular junction disorganization." (PMID 34944654, 2021). "Il20 is a member of the interleukin 10 family, which can limit the damage caused by virus and bacterial infection and also help to heal infection or inflammation of the tissue damage process." (PMID 30245729, 2018). "In sera of WT mice, IL-20RA cytokines, but not IL-10, IL-12, or IFN-γ, were detected in mock-infected animals, and EV-A71 infection significantly increased IL-19 and slightly increased IL-20 levels." (PMID 41550952, 2025). "EV-A71 infection enhanced IL-19 levels from 1 to 5 d.p.i., with significant increases on 3 and 5 d.p.i., and slightly increased IL-20 levels on 3 and 5 d.p.i. and IL-24 levels on 1 d.p.i.." (PMID 41550952, 2025). "Importantly, both IL-15 and IL-20 have been implicated in fibrosis, suggesting that Chlamydia-infected endocervical epithelial cells may produce a wider portfolio of fibromodulatory cytokines relative to infection of other cell types." (PMID 37874141, 2023). "We observe both steady-state and infection-associated induction of pro-inflammatory and pro-fibrotic signaling in the former, including increased expression of TGFA, IL6, IL8, and IL20." (PMID 37874141, 2023). "Using WB, the translation of il20rb in HaCaT cells after treatment with 400 ng of IL-20 and infection by RH-WT or RH-Δrop18 was detected at 30 min post-infection." (PMID 32767999, 2020). "Although weak STAT3-Y705 phosphorylation was still observed in these treatment groups at 24 h post-infection, the STAT3-Y705 phosphorylation observed in the RH-WT infected group was stronger than that observed in IL-20 treatment or RH-Δrop18 infection group." (PMID 32767999, 2020). "Of the immune genes with the most significantly systemically increased transcript levels only on Day 7, all except for two (Il-20 and Defb6) had significant increases in transcripts locally by one day after infection." (PMID 25901897, 2015). "As all three mouse IL-20RA cytokines are constitutively expressed and IL-10 is induced after infection, this suggests that both IL-19 and IL-20 could be the upstream effectors to induce IL-10." (PMID 41550952, 2025). "Notably, both IL-19 and IL-20 suppress IL-12 in macrophages, which protects mice from EV-A71 infection." (PMID 41550952, 2025). "The IL-20 cytokine subfamily is an important member of the IL-10 family, playing key roles not only in maintaining epithelial homeostasis and integrity but also in regulating tissue repair processes following infection or inflammation." (PMID 41288708, 2025). "Moreover, we recently demonstrated that IL-20 cytokines alter the epithelial barrier in the context of virus-induced exacerbation of COPD in mice by favoring the impact of the infection on the disorganization of intercellular junction protein." (PMID 37887308, 2023). "However, expression of specific fibromodulatory interleukins (e.g., IL7, IL15, and IL20) was enhanced only in Chlamydia-infected HCECs, suggesting a cell type-specific response to infection." (PMID 37874141, 2023). "The early phase (3 h post-infection [hpi]) is characterized by the upregulation of several genes for proinflammatory cytokines related to the mucosal immune response (il17a/f1 and il20) along with genes for antiviral cytokines (il12β) and antiviral factors (ifna and ifnc)." (PMID 35432241, 2022). "In addition, gene IL20 has a significant change of expression in the initial infection." (PMID 30769958, 2019). "Immunohistochemistry revealed altered levels of IL20, IL17A, IL4, and psoriasin, which are involved in infection." (PMID 39337422, 2024).
infection (continued). "Altogether, these data showed that infection by PVM increased the expression and the secretion of IL-20 cytokines with a different timing according to the cytokine and the compartment." (PMID 34944654, 2021). "In the Jak-STAT signalling pathway 12.4% of the genes were differentially expressed at the beginning of infection, including greatly increased expression (>10 fold) of IL6, IL7R, IL11 and IL20." (PMID 23326599, 2013). "Interestingly, IL-20 has been previously shown to play a rather negative role in host defense; infection with Staphylococcus aureus led to the early up regulation of IL-20 family members (IL-19, IL-20 and IL-24), inhibiting the local generation of IL-1β and IL-17A." (PMID 26023727, 2015). "In the present study, mRNA coding for cytokines and cytokine receptors involved in the JAK-STAT pathway, including IL19, IL20, IL21R, and IL22RA2, were highly expressed in lower trachea during host-adapted swH1N1 infection compared to non-adapted huH1N1 infection." (PMID 39247193, 2024).
kidney disease (4 papers, 2020 to 2025). "Hypoxia, a critical factor in the pathogenesis of kidney disease, also stimulates IL-20 expression in different type cells (HaCaT cells, HEK293 cells, chondrocytes, glioblastoma cells, and HUVECs)." (PMID 32028746, 2020). "In the end, we will summarize the impact of IL-20 in the renal lesion and discuss the effect of IL-20 blockade in kidney disease therapy." (PMID 32028746, 2020). "Our data confirmed the significance of IL-19, IL-20 and IL-24 in the pathomechanism of renal diseases." (PMID 32306980, 2020). "We summarized the renal target cells of IL-20 and the possible regulating role of IL-20 in the pathogenesis of kidney diseases." (PMID 32028746, 2020). "We expect to see new clinical trials to validate the efficacy of using anti–IL-20 mAb for treating kidney diseases in the near future." (PMID 32028746, 2020). "We examined the renal presence of IL-19, IL-20, and IL-24, and their receptors in animal models of different kidney diseases and in renal biopsies of patients with different renal diseases." (PMID 32306980, 2020). "We also discuss the role of IL-20 in kidney diseases and provide a potential therapeutic approach of IL-20 blockade for treating renal diseases." (PMID 32028746, 2020). "Together, these data indicate that anti-IL-20 mAb might have a therapeutic potential to ameliorate kidney disease, including renal hypertrophy, inflammation, and fibrosis." (PMID 32028746, 2020). "Recently, the role of IL-19, IL-20 and IL-24 has been reported in renal disorders." (PMID 32306980, 2020). "The expression of Il19, Il20 and Il24 increased in the animal models of various kidney diseases." (PMID 32306980, 2020). "Renal Il19, Il20 and Il24 expression was determined in ischemia/reperfusion, lipopolysaccharide, streptozotocin, or UUO induced animal models of kidney diseases." (PMID 32306980, 2020).
bone disorder (1 paper, 2018). "This review article provides an overview describing the IL-20’s biological functions in the common bone disorders and thus providing a novel therapeutic strategy in the future." (PMID 29690863, 2018).
brain disorder (1 paper, 2018). A disease affecting the brain or part of the brain. "While it is clear that glia can be a significant source of IL-10, IL-19 and perhaps IL-20 and IL-24, and these resident CNS cells are responsive to their actions, the functions of the IL-10 cytokine family in health and brain disorders have been understudied." (PMID 30542269, 2018).
gastrointestinal disease (1 paper, 2018). A disease that occurs in the gastrointestinal system, excluding the hepatobiliary system. "Targeting individual members of the IL-20 cytokine family in mice may ultimately pave the way for this cytokine system as a target for therapy of gastrointestinal diseases." (PMID 29967613, 2018).
immune diseases (1 paper, 2018). "Furthermore, several key genes (e.g., Csf1r, Ifnb1, IL-20, IL-22, IL-24, Jhdm1d, Csf1r, Ifnb1, IL-20, IL-22, IL-24, and Tgfb2 that regulate sex differences in immune diseases) were discovered." (PMID 30246031, 2018).
peripheral neuropathy (1 paper, 2021). A disorder affecting the peripheral nervous system. "Furthermore, suppression of IL-20, a proinflammatory cytokine, with IL-20 neutralizing antibody alleviated paclitaxel-induced peripheral neuropathy in animal models." (PMID 33754020, 2021).
IL20 also shares sentences with these, for which no sentence is quoted: psoriatic arthritis (3 papers); gastrointestinal infections (2); infectious disease (2); Osteopenia (2); Stroke (2); viral hepatitis (2); adenocarcinoma (1); African trypanosomiasis (1); Alzheimer disease (1); bacterial infection (1); bone metastasis (1); colorectal carcinoma (1); Crohn disease (1); dementia (1); Diarrhea (1); endometrial carcinoma (1); eosinophilic esophagitis (1); fibrosarcoma (1); folliculitis (1); glioma (1); Hepatitis (1); inflammation (1); Intestinal Diseases (1); Iron deficiency anemia (1); joint disease (1); Lewis lung carcinoma (1); metabolic dysfunction-associated steatohepatitis (1); nephritis (1); neurological diseases (1); neuropathy (1).
A further 13 diseases each share a sentence with IL20 in 1 paper.